CCL3 (C-C motif chemokine ligand 3)
Diseases named in the same sentence as CCL3 in open-access papers (continued):
Sharing a sentence is not in itself a finding about the gene and the disease.
osteomyelitis (5 papers, 2014 to 2026). An acute or chronic inflammation of the bone and its structures due to infection with pyogenic bacteria. "We identified that significant infiltration of Arg1+Sdc4+, Cxcl1+Ccl4+, and Mif+Cd63+ macrophages may affect osteomyelitis through the Ccl3-Ccr1 and Cxcl2-Cxcr2 signaling pathways." (PMID 41836400, 2026). "Additionally, elevated expression of CCL-3 can be found in aseptic implant loosening and osteomyelitis providing evidence of CCL-3 inducing differentiation of monocytes to bone-resorbing osteoclasts." (PMID 30305140, 2018). "Besides, in osteomyelitis, the expression of macrophage-related inflammatory proteins CXCL2 (MIP2α) and CCL3 (MIP1α) is related to the inflammation and bone degradation of osteomyelitis." (PMID 33868316, 2021). "In a series of in vitro studies, we were now able to show that CCL3 induced the differentiation of CD14+ monocytes to osteoclasts, which might be relevant for bone degradation in osteomyelitis, because peripheral blood monocytes are known to be osteoclast precursors." (PMID 24795505, 2014).
osteoporosis (5 papers, 2020 to 2025). A condition of reduced bone mass, with decreased cortical thickness and a decrease in the number and size of the trabeculae of cancellous bone (but normal chemical composition), resulting in increased fracture incidence. "Moreover, the secretion of chemokines, such as CCL2 and CCL3, underscores the inflammatory context associated with osteoporosis, which could further accelerate bone remodeling processes." (PMID 40564069, 2025). "Previous report revealed that the serum level of CCL3 was significantly with the increased tartrate-resistant acid phosphatase and the severity of osteoporosis in females." (PMID 32478376, 2020). "In osteoporosis, chemokines that affect osteoblast and osteoclast activity include CCL5, CCL3, and CCL4." (PMID 41416066, 2025). "Elevated circulating levels of CCL2, CCL3, CCL4, and CCL5 have been reported in patients with osteoporosis, suggesting that excessive chemokine signaling may enhance osteoclast recruitment and inflammatory bone resorption." (PMID 41416066, 2025).
status epilepticus (5 papers, 2011 to 2021). Status epilepticus is defined as a continuous seizure lasting more than 30 min, or two or more seizures without full recovery of consciousness between any of them. "During the inflammation, chemokines such as CCL2, CCL3, and CCL 5 can activate pathways leading to status epilepticus." (PMID 31632233, 2019).
tauopathy (5 papers, 2020 to 2025). Neurodegenerative disorders involving deposition of abnormal tau protein isoforms (tau proteins) in neurons and glial cells in the brain. "recently showed that the cytokine receptor CCR5 (which binds IFN‐I‐associated ligands for MIP‐1a/CCL3, MIP‐1b /CCL4, and CCL5) promoted tauopathy in in vivo models, partially through the regulation of autophagy." (PMID 37849026, 2024). "Ccl3 was identified as one of the common top hits in microglial transcriptome profiling from aging, amyloidosis, and tauopathy models." (PMID 34731000, 2021). "In accordance with our data, increased CCL3 production by microglial cells was observed in a different model of tauopathy, THY-Tau22 mice." (PMID 32508844, 2020). "Recent research revealed that microglial-derived CCL3/4/5 activates neuronal CCR5 to suppress neuronal autophagy in Huntington’s disease and tauopathies." (PMID 40089481, 2025). "Moreover, microglia-derived CCL3/4/5 activates neuronal CCR5, leading to autophagy inhibition and accumulation of protein aggregates in mouse models of Huntington's disease and tauopathy." (PMID 38084916, 2024).
acute pancreatitis (4 papers, 2021 to 2024). An acute inflammatory process that leads to necrosis of the pancreatic parenchyma. "Additionally, CCL3 induces inflammatory responses in acute pancreatitis (AP) by activating the JNK/ p38 MAPK signaling pathway." (PMID 38730482, 2024).
alcoholic fatty liver (4 papers, 2012 to 2022). "Unlike in a previous report, however, patients with simple fatty liver also showed a trend of increased serum CCL3 levels and a significant increase in hepatic CCL3 protein expression compared with those of healthy controls." (PMID 35744024, 2022). "The improvements in plasma lipids might be explained by the reduced hepatic steatosis in recipients of CCL3−/− bone marrow." (PMID 22359597, 2012).
alveolitis (4 papers, 2013 to 2024). "Interestingly, CCL3 levels are increased in the serum and bronchoalveolar fluid of SSc patients and associated with alveolitis and interstitial lung disease." (PMID 28223983, 2017). "Reflecting the significant reduction in expression of chemokines (CCL3, CCL4, CXCL1, CXCL2, and CXCL10) in the lung, the levels of alveolitis in PKD1mKO at 24 h after the S. rectivirgula exposure was also significantly reduced compared to the levels of alveolitis in WT." (PMID 39464896, 2024).
bacterial meningitis (4 papers, 2013 to 2016). Inflammation of the membranes surrounding the brain and spinal cord due to a bacterial infection. "Both MIP-1 (CCL3) and MIP-2 (CCL3) are produced by immune cells resident in the brain and attract monocytes and neutrophils from the bloodstream into the CSF in acute bacterial meningitis." (PMID 23997430, 2013). "Additionally, pyroptosis causes the excessive production of cytokines and chemokines including TNF-α, IL-1β, IL-6, CCL3, CXCL-1, CXCL-2, etc. in bacterial meningitis which can also result in inflammatory mediator-induced neuronal damage." (PMID 26683708, 2015).
breast tumors (4 papers, 2015 to 2020). "However, in the breast tumor cells lines MDA-435S and MCF-7, chronic hypoxia increases the expression CCL3/MIP-1α." (PMID 32781743, 2020).
cardiomyopathy (4 papers, 2013 to 2025). A disease of the heart muscle or myocardium proper. "This would confirm the role that certain inflammatory cytokines (IFNγ, TNFα, or CCL3) play in the induction of cardiac pathologies (cardiomyopathy and QTc prolongation) in the disease." (PMID 40623042, 2025). "Initially, we validated our experimental model to study the contribution of CCL3 in the pathophysiology of T. cruzi-induced cardiomyopathy." (PMID 32194558, 2020). "Inspection of CK-MB isoenzyme activity serum, a marker of cardiomyocyte lesion and cardiomyopathy severity in experimental CCC, revealed that CK-MB levels were increased in infected ccl3+/+ mice compared with NI mice." (PMID 32194558, 2020).
chlamydial infection (4 papers, 2008 to 2025). "In our study, we observed a release of MIP-1α/β (CCL3/4) into the supernatant after chlamydial infection and/or irradiation." (PMID 25019934, 2014). "CCL3 and CCL4 are also CCR5 ligands, but these chemokines were not remarkably elevated compared to CCL5, which was the most abundant CCR5 ligand expressed during the early stages (i.e., < 7 days) of chlamydial infection." (PMID 18700040, 2008).
diabetic neuropathy (4 papers, 2018 to 2025). A chronic, pathological complication associated with diabetes mellitus, where nerve damages are incurred due to diabetic microvascular injury involving small blood vessels that supply these nerves, resulting in peripheral and/or autonomic nerve dysfunction. "Collectively, the literature data on diabetic neuropathy or CCI consistently reveals that increased levels of CCL3 are associated with neuropathic pain symptoms." (PMID 41153795, 2025). "CCL3 is involved in diabetic neuropathy as a neutralizing antibody against this chemokine reduces STZ-induced tactile and thermal hypersensitivity measured 7 days after STZ injection." (PMID 39457105, 2024). "Therefore, the findings of studies investigating the role of CCL3 in diabetic neuropathy cannot be directly extrapolated to CIPN." (PMID 41153795, 2025). "Rats with diabetic neuropathy have increased Ccl3 levels in the spinal cord, but not in the sciatic nerve, 3–4 weeks after STZ injection." (PMID 39457105, 2024). "Additionally, it has been shown that CCR5, CCL2, CCL3, CCL5, CCL7, CCL8, and CCL12 spinal mRNA and/or protein levels are elevated in rodent models of diabetic neuropathy, with some displaying sex-related diversity." (PMID 39457105, 2024). "Therefore, determining the role of C–C motif chemokine ligands in the MIP-1 family (namely, CCL3, CCL4, CCL9) in the development of diabetic neuropathy is highly important." (PMID 29593735, 2018). "We give evidence that CCL3 and CCL9, based on their spinal upregulation and strong pronociceptive properties, might be important factors involved in the development of diabetic neuropathy." (PMID 29593735, 2018).
disc degeneration (4 papers, 2018 to 2024). "CCL3, which is also known as macrophage inflammatory protein 1-alpha (MIP-1-α) in NP, has been reported to promote macrophage infiltration disc degeneration." (PMID 30585203, 2018).
endotoxemia (4 papers, 2009 to 2021). "However, future detailed analyses of CCL3, IL-16, and IL-1α in this setting might provide additional insights into potential mechanisms mediating the observed protection against endotoxemia." (PMID 29928698, 2018).
gastritis (4 papers, 2024 to 2025). Inflammation of the stomach. "Our study identifies an association between CCL3 and H. pylori-related gastritis, which leads to the damage of the gastric mucosa." (PMID 38730482, 2024). "Therefore, inhibiting the secretion of CCL3 or blocking P38 phosphorylation may become new targets for improving gastric mucosal damage, providing new insights into the pathogenic mechanism and treatment of H. pylori-related gastritis." (PMID 38730482, 2024).
Hypercalcemia (4 papers, 2017 to 2025). An abnormally increased calcium concentration in the blood. "Moreover, the overexpression of CCL3 also positively associated with hypercalcemia, implying that CCL3 may regulate the bone resorption." (PMID 32478376, 2020).
kidney damage (4 papers, 2018 to 2025). "Previous reports have established that IL-1α can act as a proinflammatory signal for kidney damage, where as Eotaxin and MIP-1α (CCL3) are potent chemokines that contribute to the recruitment of immune cells and promote AKI." (PMID 41347022, 2025). "Since IL-16 and CCL3 are both potent chemoattractants for T and NK cells and known molecules involved in cell-mediated kidney damage, this indicates a distinct role of the suPAR molecule for kidney tissue inflammation and subsequent organ damage." (PMID 37036003, 2023). "Although the association of CCL3 with aldosterone/salt-induced nephropathy has not been studied to date, these previous studies suggest a significant role for CCL3 in the pathogeny of kidney damage." (PMID 35743123, 2022).
leprosy (4 papers, 2013 to 2025). Leprosy is a chronic infectious disease affecting primarily the skin and peripheral nervous system. "Finally, several genes clustered in the 17q11–q21 region, such as chemokines CCL2, CCL3, CCL4, CCL5 and CCL7, were also linked to leprosy." (PMID 23798993, 2013). "Plasma levels of the chemokines CCL2, CCL3 and CCL11 can be detected in patients with leprosy lesions and remain unchanged after leprosy treatment." (PMID 38381878, 2024). "Samples from leprosy patients showed down-regulation of CCL2, CCL3, CCL4 (p<0.05), while IL1β and SOD2 were borderline significant (p<0.1), confirming a repression of these genes by M. leprae ex vivo, as was observed in vitro in THP-1." (PMID 23798993, 2013). "In the case of leprosy, we believe that the mediators CXCL8, CCL3, CXCL10, IL-9, IL-6, and IFN-γ could be considered as potential biomarkers for the future development of rapid assays that could assist in the diagnosis and prognosis of leprosy and leprosy reactions." (PMID 40109344, 2025).
leptospirosis (4 papers, 2016 to 2024). A contagious bacterial infection caused by spirochetes of the genus Leptospira. "The correlation analysis of detected chemokines CXCL11, CXCL9, CCL3, and CCL2 helps to clarify the role of each cytokine in leptospirosis." (PMID 39534703, 2024). "Pro-inflammatory cytokines and enzymes which were IL-1β, IL-6, TNF-ɑ, IFN-γ and COX-2 and chemokines CXCL10/IP-10 and CCL3/MIP-α showed upregulation as reported in both human and animal leptospirosis." (PMID 35584087, 2022). "This study deciphered haemorrhage as the earliest manifestation of severe leptospirosis and high levels of IL-1β, CXCL10/IP-10, CCL3/MIP-α, neutrophils and low levels of lymphocytes and platelets serve as a cumulative panel of biomarkers in severe leptospirosis." (PMID 35584087, 2022). "High levels of IL-1β, CXCL10/IP-10, CCL3/MIP-α, neutrophils and low levels of lymphocytes and platelets might serve as a cumulative panel of biomarkers in severe leptospirosis." (PMID 35584087, 2022). "Both MIP-1α/CCL3 and IP-10/CXCL10 chemokines are important chemotaxis potents on leucocytes and murine models of the disease showed infiltration of CD11b+ macrophages and CD3+ lymphocytes in renal tissues during chronic leptospirosis." (PMID 27219334, 2016). "The increased expression of IL-1β, CXCL10/IP-10, CCL3/MIP-α, high neutrophils and low lymphocytes and platelets production observed in the present study indicate that these parameters could serve as a cumulative panel of biomarkers in severe leptospirosis." (PMID 35584087, 2022). "The early expression of IL-1β, CXCL10/IP-10 and CCL3/MIP-α, increase of neutrophils and decrease of lymphocytes and platelets suggesting that these parameters could be used as a cumulative panel for potential biomarkers in severe leptospirosis." (PMID 35584087, 2022). "Taken all these data together, we suggest that high levels of IL-1β, CXCL10/IP-10, CCL3/MIP-α, neutrophils and low levels of lymphocytes and platelets could serve as a cumulative panel of potential biomarkers in the disease progression from mild to severe in leptospirosis." (PMID 35584087, 2022).
liver diseases (4 papers, 2020 to 2024). "Disease annotations suggested three of the proteins are linked to different types of cancer (CDCP1, CCL3, ITGA11), whereas another two are related to liver diseases (CXCL10, HGF)." (PMID 36737481, 2023).
macrophage activation syndrome (4 papers, 2020 to 2021). A complication of rheumatic disease that is caused by excessive activation and uncontrolled proliferation of T lymphocytes and well-differentiated macrophages. "Careful observation revealed that the excessive cytokines and chemokines activated by macrophages (i.e., IL-6, IL-7, TNF-α, CCL-2/MCP-1, CCL-3/MIP-1α) were similar to results previously found in hemophagocytic lymphohistocytosis (HLH) and macrophage activation syndrome (MAS)." (PMID 32922406, 2020). "Cytokine storm, defined as macrophage activation syndrome (MAS), is characterized by the release of multiple pro-inflammatory cytokines (IL-1β, IL-18, IL-6, IL-2, IL-7, TNF-α) and chemokines (CCL2, CCL3) from macrophages." (PMID 35008658, 2021).
osteoarthritis (4 papers, 2018 to 2025). A noninflammatory degenerative joint disease occurring chiefly in older persons, characterized by degeneration of the articular cartilage, hypertrophy of bone at the margins and changes in the synovial membrane. "We performed immunohistochemical staining to explore the expression patterns of chemokines (CCL13, CCL18, and CCL3) in the synovial membrane of RA subgroups, while the osteoarthritis (OA) synovial membrane was used as controls." (PMID 34404786, 2021).
pneumonitis (4 papers, 2010 to 2020). An inflammatory process affecting the lung parenchyma. "SsRNA stimulation of human leukocytes induced cytokines/chemokines similar to those observed in murine SARS-CoV pneumonitis including IL-1α, IL-1β, IL-6, TNF, CXCL8 (IL-8), CCL2 (MCP-1), CCL3 (MIP-1α), and CCL4 (MIP-1β)." (PMID 23236475, 2012).
renal cell carcinoma (4 papers, 2015 to 2024). "For example, the axis of CCL3 and one of its receptors, CCR5, has been associated with lung metastasis in murine renal cell carcinoma." (PMID 39684816, 2024). "Aside from IL-8, additional factors including IL-1β, CCL2, CXCL5, IL-17 and IL-18 also selectively recruit subsets of MDSCs from the vasculature into renal cell carcinoma while CCL3 and CCL5 are important for the retention of MDSCs in tumors." (PMID 38726320, 2024).
Sandhoff disease (4 papers, 2008 to 2018). A lysosomal disorder from the GM2 gangliosidosis family, caused by biallelic pathogenic variants in the HEXB gene, characterized by GM2 ganglioside accumulation in the nervous system and progressive central nervous system degeneration. "Previously, we observed that deletion of the inflammatory chemokine Ccl3 gene did not have the beneficial effect on neurodegeneration in NPC-diseased mice that was evident for another lysosomal storage disorder, Sandhoff disease." (PMID 22985423, 2012).
Splenomegaly (4 papers, 2013 to 2021). Abnormal increased size of the spleen. "Here, splenomegaly was similarly detected in ccl3+/+ (3.29 ± 0.31 mg/g in NI vs. 9.68 ± 0.58 mg/g in infected ccl3+/+ mice; p < 0.001) and ccl3−/− (3.78 ± 0.17 mg/g in NI vs. 8.93 ± 0.49 mg/g in infected ccl3−/− mice; p < 0.001) T. cruzi-infected mice." (PMID 32194558, 2020). "Ltr7 controls splenomegaly (in interaction with Ltr5) and in interaction with Ltr3 level of both CCL3 and CCL5 in serum." (PMID 23875032, 2013). "However, CCR5-knockout MRL/lpr mice exhibited increased splenomegaly and elevated circulating/renal CCL3, suggesting that renal-infiltrating immune cells may use alternative chemokine receptors responding to CCL3 such as CCR1 to migrate into the kidney and promote LN." (PMID 27403037, 2016).
temporal lobe epilepsy (4 papers, 2015 to 2024). A localization-related (focal) form of epilepsy characterized by recurrent seizures that arise from foci within the temporal lobe, most commonly from its mesial aspect. "Furthermore, an increase in CCL3 was observed in model of temporal lobe epilepsy in the brain of rats and lipopolysaccharide-induced brain injury." (PMID 38612597, 2024). "Recently, it has been proven that CCL3 regulates synaptic plasticity mechanisms involved in learning processes and memory in mice, and changes in CCL3 have also been demonstrated in rat temporal lobe epilepsy." (PMID 38612597, 2024). "Further highlighting the clinical relevance of these chemokines, elevated CCL2 protein was observed in the temporal lobe and hippocampus from patients with intractable epilepsy, and both CCL2 and CCL3 proteins were elevated in temporal lobe epilepsy patients measured with multiplex assay." (PMID 26133170, 2015).
trauma (4 papers, 2012 to 2024). "This idea is further corroborated by the recent finding that CCL3 deficiency strongly increases inflammatory cell infiltration after experimental traumatic brain injury." (PMID 26640428, 2015). "It has been previously shown that C1-inhibitor protects from focal brain trauma in mice by reducing thrombo inflammation and diminishing upregulation of proinflammatory factors, such as CCL2, CCL3, IL-beta, and tumor Necrosis Factor alpha (TNF-α)." (PMID 33375205, 2020).
ulcerative colitis (4 papers, 2009 to 2025). An inflammatory bowel disease involving the mucosal surface of the large intestine and rectum. "For instance, the up-regulated expression of chemokines, such as CCL2, CCL3, CCL4, CCL7, CCL8 and CXCL8 has been shown in mucosal biopsies from patients with CD and ulcerative colitis, and this up-regulation correlated with the disease activity." (PMID 19421322, 2009).